PMFBP1 (polyamine modulated factor 1 binding protein 1)
Description:
Required for normal spermatogenesis. It functions as a scaffold protein that attaches the sperm head-tail connecting piece to the nuclear envelope, thus maintaining sperm head and tail integrity. May also be involved in the general organization of cellular cytoskeleton (By similarity).
Synonyms: SPGF31; STAP
Tractability: No criterion of Open Targets' tractability assessment is met for any kind of drug.
Gene: Protein-coding gene on chromosome 16 (72,112,157 to 72,176,878, reverse strand). Ensembl gene ENSG00000118557.
Subcellular location: Cell projection, cilium, flagellum
Subcellular location (Human Protein Atlas): Connecting piece; Nucleoplasm; Acrosome; Cell Junctions; Flagellar centriole; Mid piece; Principal piece
Gene Ontology:
Biological process: spermatogenesis
Cellular component: sperm head-tail coupling apparatus; sperm midpiece; sperm principal piece; cytoplasm; motile cilium; sperm flagellum; sperm head
Genetic constraint (gnomAD): Loss-of-function variants: 127 observed, 142.89 expected, observed/expected ratio (o/e) 0.89, 90% interval 0.77 to 1.03. The upper end of that interval is the gene's LOEUF score, 1.03, which puts it in group 4 of 6, group 1 being the genes least tolerant of losing a copy. Missense variants: 1,184 observed, 1,214.6 expected, observed/expected ratio (o/e) 0.97, 90% interval 0.93 to 1.02. Synonymous variants: 483 observed, 470.52 expected, observed/expected ratio (o/e) 1.03, 90% interval 0.95 to 1.11.
Homologues: Orthologues: chimpanzee PMFBP1 (99% identical), macaque PMFBP1 (94% identical), dog PMFBP1 (79% identical), pig PMFBP1 (76% identical), rat Pmfbp1 (71% identical), mouse Pmfbp1 (71% identical), rabbit PMFBP1 (68% identical), guinea pig PMFBP1 (62% identical), tropical clawed frog pmfbp1 (25% identical), zebrafish pmfbp1 (5% identical).
Diseases named in the same sentence as PMFBP1 in open-access papers:
PMFBP1 is named in the same sentence as 8 diseases in open-access papers, as found by Europe PMC text mining. Sharing a sentence is not in itself a finding about the gene and the disease. The quoted sentences say what the papers report.
acephalic spermatozoa syndrome (5 papers, 2021 to 2025). "This study identifies a novel homozygous nonsense mutation in PMFBP1 (c.2641C>T, p.Arg881Ter) in an infertile male patient with acephalic spermatozoa syndrome (ASS) who experienced assisted reproductive technology (ART) failure." (PMID 41462896, 2025). "One gene we identified was PMFBP1 (polyamine modulated factor 1 binding protein 1), mutations in which appear to cause acephalic spermatozoa syndrome." (PMID 35312700, 2022). "Here the authors demonstrate that CENTLEIN links and controls the interaction between SUN5 and PMFBP1, indicating that its impairments might be associated with acephalic spermatozoa syndrome." (PMID 34389728, 2021). "PMFBP1 in mammals was recently shown, through implication in acephalic spermatozoa syndrome, to be a necessary structural protein in sperm." (PMID 35312700, 2022). "Defects in SUN5 and PMFBP1 are the most common etiologies of human acephalic spermatozoa syndrome, as identified by different investigators and demonstrated in a mouse model." (PMID 34422805, 2021). "In human and mouse, the protein PMFBP1 is related to acephalic spermatozoa syndrome." (PMID 35312700, 2022). "We demonstrate that CENTLEIN directly interacts with both SUN5 and PMFBP1, two proteins localized in the HTCA and related with acephalic spermatozoa syndrome." (PMID 34389728, 2021).
Infertility (5 papers, 2021 to 2025). "Subsequently, mutations in SUN5 and PMFBP1 are reported in more infertile men with ASS by different laboratories, confirming a predominant contribution of these two gene mutations to human ASS." (PMID 38616611, 2024). "In humans and mouse, PMFBP1 is essential for spermatogenesis, and mutations of this gene are associated with acephalic spermatozoa, which cause infertility." (PMID 35312700, 2022). "Mutations in PMFBP1 cause acephalic spermatozoa syndrome that leads to infertility in male mice." (PMID 34408768, 2021). "PMFBP1 is also specifically expressed in the neck region of sperm and Pmfbp1-KO male mice are infertility due to the production of acephalic spermatozoa." (PMID 38616611, 2024).
male infertility (3 papers, 2021 to 2025). The inability of the male to effect fertilization of an ovum after a specified period of unprotected intercourse. "This study expands the clinical mutational spectrum of PMFBP1-associated male infertility and provides valuable insights for the genetic diagnosis of ASS patients." (PMID 41462896, 2025). "Therefore, PMFBP1 mutation is believed to play a significant role in acephalospermia, which can cause male infertility." (PMID 39668357, 2024).
teratozoospermia (1 paper, 2025). "This mutation leads to sperm head–tail detachment, expands the mutational spectrum of PMFBP1 and reinforces that truncating mutations in this gene are a well-established cause of such severe teratozoospermia." (PMID 41462896, 2025).
thymoma (1 paper, 2024). A neoplasm arising from the epithelial cells of the thymus. "It was discovered that A2M, C3, LGALS3BP, PMFBP1, and SRI were remarkably upregulated in individuals with thymoma (P < 0.05)." (PMID 39434140, 2024).
cancer (1 paper, 2024). A tumor composed of atypical neoplastic, often pleomorphic cells that invade other tissues. "Despite dysregulation in certain cancers, the expression levels of CR1 and PMFBP1 remained at a superficial level." (PMID 39434140, 2024).
PMFBP1 also shares sentences with these, for which no sentence is quoted: asthenospermia (1 paper); oligospermia (1).